INS (insulin)
Diseases named in the same sentence as INS in open-access papers (continued):
Sharing a sentence is not in itself a finding about the gene and the disease.
diabetes (continued). "Type 1 DM (T1DM) or insulin-dependent diabetes mellitus (IDDM) mainly refers to reduced circulating insulin due to pancreatic beta cell failure (American Diabetes Association, 2017)." (PMID 37346806, 2023). "Type 2 diabetes mellitus (T2DM) is a metabolic disorder that causes elevated blood glucose levels due to compromised insulin function and/or release." (PMID 37631314, 2023). "Several studies on factors associated with diabetes treatment satisfaction showed that the use of insulin is negatively associated with treatment satisfaction." (PMID 37113185, 2023). "By interfering with the GLUT-4 transporter, steroids cause a 30–50% reduction in glucose uptake in the muscle cells from insulin, increasing insulin resistance and hyperglycemia with an increased risk of diabetes mellitus." (PMID 36769807, 2023). "During Period 2 the variables “diabetes”, “use of IV insulin”, “use of SC insulin”, and “SOFA score” were significantly associated with higher blood glucose levels." (PMID 37330419, 2023). "For example, there is an increased risk of obesity, dyslipidemia, and diabetes, and insulin dysfunction and impaired glucose tolerance are induced." (PMID 36771468, 2023). "These genetically modified mice develop insulitis at around 3 to 4 weeks of age and around 90% of pancreatic insulin is lost, leading to the onset of diabetes and rapid weight loss from 10th to 14th weeks." (PMID 38068983, 2023). "Diabetes mellitus is a group of metabolic diseases characterized by hyperglycemia due to deficiency in insulin secretion, insulin action, or both." (PMID 37440921, 2023). "Vascular damage is often one of the first central events in diabetes, even in the prediabetic stages, and compensatory high insulin levels are sufficient to cause this damage." (PMID 37873836, 2023). "ARBs are antihypertensive drugs that provide additional benefits, including a reduction in diabetes risk, enhancement of insulin sensitivity, and reduction in microalbuminuria." (PMID 37121975, 2023). "Despite the higher prescription costs of insulin pens than vial syringes, previous studies reported similar or even lower all-cause and diabetes-related total annualized healthcare costs." (PMID 36782190, 2023). "JAZF1 has been implicated in glucose and lipid homeostasis, insulin signaling, and metabolic disorders such as diabetes." (PMID 37091973, 2023). "Fundamentally, diabetes is characterized by the inability to maintain blood glucose homeostasis due to loss and/or dysfunction of insulin-producing β cells." (PMID 38007492, 2023). "Its regulation of energy homeostasis, improvement of insulin sensitivity and induction of weight loss with the related potential in the treatment of obesity and diabetes have garnered massive scientific attention in the last years." (PMID 36642986, 2023). "Zinc is a crucial micronutrient and zinc deficiency is positively associated with diabetes, owing to the involvement of zinc in insulin production, storage, and secretion, and it being known to improve the structural integrity of insulin." (PMID 37374226, 2023). "Considering the pancreas, it is well known that the loss of insulin-secreting ß-cells because of either autoimmune processes or surgical resection of the pancreas is responsible for Diabetes mellitus (DM)." (PMID 36810405, 2023). "It has been reported that there is association between increased TNF-α levels in diabetes and impaired insulin signaling possibly by increasing IRS-1 serine phosphorylation." (PMID 37089941, 2023). "Loss of β-cells function and impaired insulin secretion in obesity and diabetes results in persistent hyperglycemia and dyslipidemia." (PMID 37089941, 2023). "Diabetes mellitus (diabetes) is a group of severe metabolic diseases characterized by increased blood glucose levels resulting from a deficiency of insulin secretion, body resistance to insulin, or both." (PMID 38137892, 2023).
diabetes (continued). "HNF1B/MODY represents up to 6% of all MODY cases and is one of the most frequent causes of syndromic diabetes, showing a decrease in insulin secretion with progressive worsening of blood glucose control." (PMID 36672242, 2023). "Diabetes mellitus type 2 has been associated with insulin resistance and/or a change in insulin secretion in cases where pancreatic β-cells are unable to produce insulin." (PMID 37110524, 2023). "Type 2 diabetes mellitus (T2DM) is a chronic degenerative disease characterized by metabolic failure caused by the combination of two factors: a reduction of insulin, and tissues developing a decreased or null sensitivity to insulin." (PMID 38255175, 2023). "Adherence to PD has been shown to increase insulin sensitivity and reduce the risk of diabetes, both of which are directly associated with obesity risk." (PMID 37468920, 2023). "Diabetes mellitus (DM) is a chronic disease that causes hyperglycemia due to defective insulin secretion or impaired biological action." (PMID 37377963, 2023). "The ketogenic diet (KD) is protective for malnutrition risk and cardiovascular complications like diabetes and obesity, by altering the homeostasis of metabolites and regulating the level of glucose sugar and insulin." (PMID 37521420, 2023). "Diabetes is a chronic endocrine disease caused by either insulin deficiency, ineffective use of insulin or both." (PMID 37032781, 2023). "As defined by the American Diabetes Association, diabetes type 2 is a chronic medical condition characterized by high glucose levels due to insulin resistance and/or inadequate insulin production by the pancreas." (PMID 37013500, 2023). "Among the T2DM patients, important risk factors for fracture were a low BMI (<25 kg/m2), long diabetes duration (≥15 years), insulin treatment, and low physical activity." (PMID 36701363, 2023). "Hyperglycemia, which is a chronic metabolic condition caused by either a defect in insulin secretion or insulin resistance, is a hallmark of diabetes mellitus (DM)." (PMID 37111281, 2023). "Impaired insulin secretion and glucose intolerance represent the primary mechanisms associated with diabetes (type 1 or type 2) and cystic fibrosis." (PMID 37893045, 2023). "In hyperglycemia/diabetes, impaired insulin signaling in the brain causes a cerebral pathology and cognitive impairments as in sporadic Alzheimer’s disease (sAD)." (PMID 37443762, 2023). "Diabetes mellitus (DM) is caused by the body's resistance to insulin or a deficiency of insulin synthesis from the pancreatic islet cells of Langerhans." (PMID 37954695, 2023). "Early menarche is associated with increased insulin levels and increased risk of type 2 diabetes mellitus." (PMID 37441710, 2023). "Sustained glucose levels above 7.2 mM are diagnosed as diabetes mellitus, defined by the American Diabetes Association as “a group of metabolic diseases characterized by hyperglycemia resulting from defects in insulin secretion, insulin action, or both”." (PMID 37134142, 2023). "T2D is the most frequent subtype of diabetes and it is characterized by alterations of blood glucose levels due to varying combinations of IR and a relative deficiency of insulin secretion by the pancreatic β cells." (PMID 36979367, 2023). "LCCP participation and higher baseline HbA1c were associated with a larger HbA1c reduction, whereas older age, longer diabetes duration, and higher baseline dose of premixed insulin analogue were associated with a smaller HbA1c reduction." (PMID 37097724, 2023). "Type 2 diabetes mellitus develops when a relative deficiency of insulin ensues from a genetic predisposition to insufficient insulin production, compounded by insulin resistance arising from an environmental predisposition to a poor lifestyle." (PMID 37570372, 2023).
diabetes (continued). "While excessive ROS will cause impaired glycometabolism in the liver, enhance insulin resistance in the liver and skeletal muscle cells, and reduce the function of pancreatic β-cells, it also promotes the development of diabetes." (PMID 36908916, 2023). "Insulin formulations with diverse oligomerization states are the hallmark of interventions for the treatment of diabetes." (PMID 36792809, 2023). "The relationship between tRNA gene mutations and diabetes mellitus starts from high blood sugar levels in the body or when the body is experiencing hyperglycemia, thereby triggering insulin secretion." (PMID 37372155, 2023). "summarized two causes of diabetes mellitus: impaired insulin action and impaired insulin secretion or a combination of both factors." (PMID 38027115, 2023). "Significant improvements in controlling glucose homeostasis and increasing insulin sensitivity can be achieved by managing weight gain and obesity, especially abdominal obesity, which has been closely linked to diabetes." (PMID 37047820, 2023). "Alloxan specifically kills the insulin-secreting cells in the pancreas, leaving less active cells and causing diabetes." (PMID 37687218, 2023). "Diabetes mellitus (DM) is a chronic disease characterized by an absolute or relative deficiency of insulin or its action that promotes hyperglycemia." (PMID 37794521, 2023). "The cause of diabetes mellitus in dogs is poorly characterized, however, initial factors such as genetic predisposition, infection, disease- and insulin-antagonistic drugs, obesity, immune-mediated mechanisms, and pancreatitis have been identified." (PMID 36830471, 2023). "Glycemic deterioration is a typical complication of COVID-19 in patients with impaired glucose regulation or diabetes and in patients requiring insulin, SARS-CoV-2 infection was associated with a rapidly increasing need for high doses of insulin." (PMID 34328581, 2023). "Our study results showed that the changed glucogenic amino acids, such as glycine, were associated with the impairment of insulin sensitivity at a later phase of diabetes progression as compared with branched and aromatic amino acid metabolism." (PMID 37569840, 2023). "Although in the specialized literature there are no guidelines dedicated to the therapy of metabolic diseases secondary to endocrinopathies, associated diabetes can usually be controlled with oral agents and rarely requires the use of insulin." (PMID 37628857, 2023). "Insulin resistance is characterized by impairment of insulin action in insulin-targeting tissues and organs such as skeletal muscles, adipocytes and the liver, and causes hyperglycemia observed in type 2 diabetes mellitus (T2DM)." (PMID 37238649, 2023). "We find that various types of novel technologies, such as devices to monitor blood sugar levels continuously or deliver insulin, improve important diabetes-related measures and can reduce the risk of having low blood sugar levels." (PMID 37794113, 2023). "Microarray expression analysis demonstrated that the increased expression of insulin signaling cascade genes in female adipose tissue contributed to reduced insulin resistance and diabetes risk compared to males." (PMID 37242132, 2023). "Diabetes mellitus (DM) is a metabolic disorder caused by decreased insulin production and is characterized by persistent hyperglycemia and abnormalities in carbohydrate, lipid, and protein metabolism." (PMID 37111190, 2023). "Lack of these T2DM risk factors and T1DM-specific markers, including diabetes autoantibodies and low C-peptide levels (as a measure of endogenous insulin production), indicates a high probability of MODY." (PMID 37016461, 2023). "Type 1 diabetes mellitus (T1DM) occurs due to the destruction of the beta cells of pancreas leading to the deficiency of insulin." (PMID 38034631, 2023).
diabetes (continued). "Screening individuals with diabetes for HU is important to minimize the risk of hypoglycemia by modifying glycemic targets and adjusting either insulin or insulin secretagogue therapy." (PMID 37964960, 2023). "In the risk predictor analysis of this study, gender, use of insulin, renal failure, duration of diabetes, UACR, blood urea nitrogen, and serum phosphorus were related to the risk of DR in midlife patients with T2DM." (PMID 37008912, 2023). "The accumulation of fatty deposits in the pancreas, which can hinder insulin secretion and increase the risk of diabetes, has been linked to increased blood levels of Apo-B-containing lipoproteins." (PMID 37123009, 2023). "Diabetes is a complex disease caused by hyperglycemia due to impaired insulin secretion and/or damaged insulin action." (PMID 37903808, 2023). "Diabetes mellitus is a multifaceted metabolic disorder characterized by high blood glucose levels (hyperglycemia), which is caused by insulin resistance or insufficient insulin production." (PMID 37299466, 2023). "The transcriptomes revealed schizophrenia as a diabetes-like condition in the brain, possibly due to deficient activation of brain receptors for insulin and muscarinic cholinergic receptors." (PMID 36651666, 2023). "Statins are associated with accelerated progression to diabetes via the mechanisms of insulin secretion, insulin resistance, and cellular metabolisms of glucose." (PMID 37213641, 2023). "In both types of diabetes, the loss of beta cells leads to hyperglycemia due to insulin deficiency, with the need for permanent insulin therapy or adjustment, to sustain a functioning glycemic balance." (PMID 37371102, 2023). "Diabetes mellitus is a metabolic disorder characterized by a defect in insulin secretion, insulin function, or both, causing hyperglycemia and other debilitating complications, including micro- and macro-vascular complications." (PMID 38666042, 2023). "A reduction or absence of insulin activity causes diabetes mellitus (DM), which is a condition that is characterized by a high blood sugar level, or hyperglycemia." (PMID 37111797, 2023). "Diabetes mellitus is a chronic metabolic disorder characterized by hyperglycemia associated with defects in insulin secretion, insulin action, or both." (PMID 37006547, 2023). "Insulin resistance (IR) is the weakening of the biological effect of the body to insulin, including the decrease in sensitivity and responsiveness to insulin, thought to be the primary cause of type 2 diabetes mellitus (T2DM)." (PMID 38068866, 2023). "Insulin-deficient diabetes or loss of insulin/IGF-1 action in muscle reduces complex I-driven mitochondrial respiration and supercomplex assembly, in part due to FoxO-mediated inhibition of complex I subunit expression." (PMID 37495991, 2023). "Several mechanisms have been suggested as potential causes for reduced glucose metabolism in relation to the development of neurodegenerative diseases, some of which can be associated with diabetes pathology and insulin depletion." (PMID 37869511, 2023). "Most of the literature associated with diabetes modeling focuses on glucose and insulin regulatory systems, diabetes pathways, diabetes epidemiology, diagnostic test evaluations, and the burden of complications." (PMID 36673694, 2023). "Use of diabetes technology including continuous glucose monitor (CGM) and insulin pump in diabetes management is associated with lower HbA1c compared to insulin injections and self-monitoring of blood glucose (SMBG)." (PMID 40303257, 2023). "According to the United Kingdom Prospective Diabetes Study, intense blood glucose control with sulfonylureas or insulin significantly reduced the risk of microvascular complications." (PMID 38155289, 2023). "Diabetes mellitus (DM) is a metabolic disease characterized by hyperglycemia and caused by defects in insulin secretion, insulin action, or both." (PMID 37821982, 2023).
diabetes (continued). "According to the American Diabetes Association, “Diabetes is a group of metabolic diseases characterized by hyperglycemia resulting from defects in insulin secretion, insulin action, or both”." (PMID 36673851, 2023). "Wondmkun emphasizes that obesity is a triggering factor for diabetes associated with insulin resistance, in which the biological effects of insulin in physiological concentrations are impaired." (PMID 37505836, 2023). "Genes implicated in the etiology of diabetes, including networks involving glucose metabolism, insulin secretion and regulation, and cell cycle regulation, were notably altered." (PMID 36815184, 2023). "We demonstrate that carriers of diabetes risk alleles in CALCOCO2 have altered insulin secretion and that loss of CALCOCO2 in human beta cells leads to autophagy-mediated altered insulin granule homeostasis." (PMID 36543916, 2023). "Diabetes mellitus is a group of metabolic diseases characterized by hyperglycemia caused by abnormalities in insulin secretion, insulin action, or both." (PMID 37554894, 2023). "Together these findings show that O304 potently and in an insulin independent manner reverts diabetes in an insulin deficient mouse model of diabetes." (PMID 37626210, 2023). "Previously published articles have reported that age, sex, BMI, hypertension, insulin concentration and hyperglycemia are all risk factors for prolonged QTc interval in patients with diabetes." (PMID 36698056, 2023). "The pathogenesis in diabetes involves adipokines-mediated blocking of insulin signaling transduction pathway, causing a progressive development of insulin resistance and eventually leading to type 2 diabetes." (PMID 37050926, 2023). "One study included four comparisons pertaining to the risk of diabetes (fasting plasma glucose [mg/dL], serum insulin [mIU/mL], homeostasis model of assessment-estimated insulin resistance, and quantitative insulin sensitivity check index)." (PMID 36879342, 2023). "Patient characteristics such as age, educational status, occupation, disease duration, and type of diabetes were significantly association with insulin injection practice (p < 0.05)." (PMID 37143082, 2023). "It is generally accepted that Zn is required in pancreatic β-cells in the process of insulin biosynthesis and the maturation of insulin secretory granules; thus, changes in Zn levels in the pancreas are associated with diabetes." (PMID 37371981, 2023). "Diabetes mellitus is a chronic metabolic disease caused by impaired insulin biological function or defective secretion of insulin." (PMID 36987204, 2023). "The pharmacotherapy of diabetes includes insulin (when insulin deficiency is seen) or oral hypoglycaemic drugs that exert anti-diabetic effects through different mechanisms." (PMID 37686786, 2023). "Diabetes mellitus (DM) is a metabolic disease characterized by chronic hyperglycemia caused by insufficient insulin secretion or defective insulin action (Classification and Diagnosis of Diabetes, 2022)." (PMID 37255749, 2023). "In terms of diabetes, polymorphisms of the calpain-10 gene can modify insulin secretion and glucose disposal." (PMID 38069105, 2023). "Diabetes mellitus is a chronic metabolic disease caused by absolute or relative deficiency of endogenous insulin or the body’s inability to efficiently utilize insulin." (PMID 37230992, 2023). "Diabetes mellitus is a metabolic disorder characterized by chronic hyperglycemia as a result of a deficiency in insulin secretion or its action or both, which leads to disturbances in carbohydrate, fat, and protein metabolism." (PMID 38067527, 2023). "Diabetes mellitus is a versatile metabolic condition that is distinguished by heightened levels of blood glucose caused by either inadequate insulin production or impaired insulin function." (PMID 37724233, 2023).